EGFR (epidermal growth factor receptor)
Diseases named in the same sentence as EGFR in open-access papers (continued):
Sharing a sentence is not in itself a finding about the gene and the disease.
tumor (continued). "Co-targeting of COX2 with BRAF + EGFR promotes durable suppression of tumor growth in patient-derived tumor xenograft models." (PMID 36759733, 2023). "We focused on GBM and lung tumors, as they are currently the only tumor types in which it has been provided evidence of an indirect CBX3-mediated regulation of EGFR and RAC1, respectively." (PMID 37633946, 2023). "In an osimertinib-resistant EGFR ex19del/T790M/C797S mouse model derived from a patient with an NSCLC tumor who progressed after treatment with gefitinib and osimertinib, the tumor growth was inhibited by BLU-945." (PMID 38201251, 2023). "In brain metastatic lung cancer, BASP1 reduces the degradation of EGFR protein via the ubiquitin–proteasome pathway and stabilizes EGFR protein, thereby promoting tumor progression." (PMID 37243901, 2023). "In a non-small cell lung cancer (NSCLC) xenograft model with EGFR overexpression, those immunoliposomes showed a strongly enhanced ability for drug delivery and tumor growth inhibition." (PMID 36678845, 2023). "The bimodal 111In-labeled DTPA-IRDye700DX VHH was found to specifically accumulate at the EGFR overexpressed tumor sites in mice bearing A431 xenografts." (PMID 37746282, 2023). "Increasing studies have reported that EGFR and its endogenous ligands were overexpressed and exert pro-tumor roles in HNSCC." (PMID 37965134, 2023). "Hereafter, the review will focus on EXO cargo, namely, proteins, RNAs, and DNA found within EXOs and MVs, with a focus on EGFR-dependent tumours." (PMID 37296932, 2023). "A previous study demonstrated that a combination of TKI afatinib with cetuximab, which reduce EGFR protein expression, exhibited an encouraged tumor response in EGFR-mutant LUADs progressing on afatinib." (PMID 37178919, 2023). "While anti‐tumor activity was observed across multiple subgroups in this study, we noted a trend towards higher ORR for patients harboring EGFR ex20ins versus other EGFR tumor mutations (41.7% vs 33.3%)." (PMID 37723837, 2023). "A previous study showed that vaccination with the extracellular domain of murine EGFR reduced lung metastasis in mice challenged with tumor cells." (PMID 36851313, 2023). "The epithelial-to-mesenchymal transformation (EMT) can be also included among these resistance mechanisms, as well as the consequent loss of cell adhesion and polarity and promote the formation of tumor stem cells and decreasing the EGFR signaling addiction." (PMID 37152062, 2023). "In the ADAURA study, osimertinib, a third-generation tyrosine kinase inhibitor that was administered as an adjuvant in EGFR mutated NSCLC, was associated with an 80% reduction of recurrence compared to placebo after surgical resection of the tumor." (PMID 37568927, 2023). "The overall mode of predominant tumor architectural patterns exhibited a statistically significant difference between EGFR mutant and wild-type slides (p = 0.035; Chi-squared test)." (PMID 36927889, 2023). "Combination TKI therapy and EGFR-MET bispecific antibodies have shown promising anti-tumor activity in early clinical trials." (PMID 37296959, 2023). "In contrast, the third-generation Osimertinib, a mono-anilino pyrimidine compound, has demonstrated sustained CNS activity and the ability to inhibit tumor growth selectively, making it an attractive option for the treatment of EGFR-Fused NSCLC." (PMID 37375228, 2023). "CD73 functions in EGFR-mediated tumor cell dissemination were addressed in 2D and 3D cellular models of migration and invasion." (PMID 37620936, 2023).
tumor (continued). "The use of targeted agents against tumor angiogenesis and EGFR is approved by the European Medicines Agency and US Food and Drug Administration (FDA) for the first- or second-line treatment of mCRC." (PMID 37496011, 2023). "Cetuximab was included as positive control, since it is known that this EGFR‐directed antibody triggers very potent NK cell‐mediated eradication of EGFR expressing tumor cells via ADCC." (PMID 36775946, 2023). "EGFR-targeted NeoAg vaccination works mainly through the activation of tumor antigen-specific CD4+ T cells and CD8+ T cells." (PMID 37766136, 2023). "Sex and tumor location influenced molecular features such as PD-L1, MMR/MSI status and EGFR expression in CRC, suggesting a possible underlying mechanism of sex-specific colorectal carcinogenesis." (PMID 36802389, 2023). "Together, these data suggest that PM can promote tumour progression in both oncogenic Kras and EGFR models of LUAD." (PMID 37020004, 2023). "The VEGF and EGFR pathways are involved in biological processes such as tumor growth and progression, angiogenesis and metastasis." (PMID 36674696, 2023). "The EGFR/AREG axis activation, coupled with the mutational patterns in PI3K/AKT/mTOR and cell cycle pathways warrants caution in considering MECs as low‐risk neoplasms." (PMID 36916425, 2023). "STAT3 is a downstream effector of c-MET/EGFR and is activated in CSCs and primarily expressed in the invasive tumor margin." (PMID 37924112, 2023). "Further questions arise when considering that most endocytic machinery have been historically considered tumor suppressors, and the sustained EGFR signaling thought to be advantageous for survival." (PMID 37752992, 2023). "Tumor gene mutations, such as those in the RAS/Raf/MEK/MAPK pathway, EGFR, and JAK genes, have been linked to ICB response." (PMID 38001644, 2023). "EGFR and another receptor tyrosine-protein kinase, c-Met, cooperatively regulate tumor cell proliferation, migration, and activation of the downstream signaling pathways." (PMID 36900399, 2023). "This phase 2 study demonstrated that the combination of sintilimab and anlotinib has promising anti‐tumor activity and is generally well tolerated in patients with advanced, pre‐treated NSCLC harboring uncommon EGFR mutations." (PMID 37723837, 2023). "Li designed CuS-Ab NPs loaded with cetuximab to target EGFR to inhibit angiogenesis and tumor growth and to promote the accumulation of CuS NPs in tumors; these NPs reduce the laser energy required for PTT therapy and reduce damage to normal tissue." (PMID 37111692, 2023). "Other reports revealed the significance of inflammation markers in predicting NSCLC survival, particularly in patients with EGFR-mutant tumours treated with tyrosine kinase inhibitors." (PMID 37120670, 2023). "Tumor stem cell marker DCLK1 is essential for maintaining tumor cell stemness via the Wnt/β-Catenin pathway and facilitates the development of EGFR-TKIs resistance." (PMID 37089959, 2023). "EGFRvIII is constitutively activated and confers dysregulated intracellular EGFR signaling, leading to uncontrolled tumor cell growth and proliferation resistance to wild-type EGFR therapeutics." (PMID 38201434, 2023). "Our results demonstrated a different benefit from third-line anti-EGFR-based therapy according to primary tumor site, confirming the role of L-sided tumor in predicting benefit from third-line anti-EGFR vs R/T." (PMID 36895480, 2023). "RE tumours had elevated baseline levels of epithelial growth factor receptor (EGFR), which is highly overexpressed in various malignancies and associated with resistance and poor prognosis." (PMID 37460712, 2023). "Targeted therapy is a hot spot in tumor treatment in recent years and the epidermal growth factor receptor (EGFR) is a promising new therapeutic target for the treatment of cancer." (PMID 37530857, 2023).
tumor (continued). "Lastly, IHC analyses of tumor tissues indicated that Gefitinib effectively reduced Phospho-EGFR and Ki67 protein levels in both control and LAMC2 groups." (PMID 37542131, 2023). "miR-128 induces its tumor-suppressing effect, such as anti-proliferative and anti-metastasis effects, by inhibiting tumor-associated signaling pathways, such as WNT, ERK, EGFR, IGF1R, or BCL2." (PMID 37371047, 2023). "EGFR over-expression is common in OSCC, correlates with tumour progression and is associated not only with gene amplification but also with multiple centromere copies of chromosome 7, due to centromere region amplification." (PMID 36671795, 2023). "Bevacizumab and EGFR inhibitor monotherapy or in combination blocked angiogenesis in tumors and inhibited tumor growth." (PMID 36646686, 2023). "Several clinical trials with EGFR inhibitors have failed because of low CNS penetrance, tumor heterogeneity, and pharmacokinetics properties." (PMID 38264122, 2023). "Further IHC analysis of the xenograft tumor sections showed that MZF1 expression was higher after EGFR-TKIs+5-Aza treatment compared with EGFR-TKIs alone." (PMID 36778111, 2023). "We suggest that coblockade of EGFR and Notch signalling can effectively suppress both bulk tumour cells and CSCs, which also promotes the response after PARP blockade in different cancer cell lines and PDX tumour models." (PMID 37441599, 2023). "FYLM treatment delays the resistance of EGFR-mutant cell lines and EGFR-mutant tumor-bearing mice to osimertinib by inhibiting the Wnt/EGFR pathway." (PMID 37841927, 2023). "The method both identifies proteins that are central in all three hormonally responsive cancers (e.g. phosphorylated EGFR) and proteins of tumor-specific relevance (e.g. CD31 in UCEC)." (PMID 38152341, 2023). "It has been reported that the activation of the PD-1/PD-L1 pathway contributes to immunosuppression during anti-tumor therapy in EGFR-driven lung tumors by suppressing T-cell function and increasing the release of pro-inflammatory cytokines." (PMID 38025757, 2023). "Given that ERRFI1 is associated with tumor development and drug resistance, we further explored the functional role of ERRFI1 in EGFR feedback activation in the context of MRTX1133." (PMID 37020035, 2023). "Reciprocal signaling between SRC and EGFR contributes to a more cancer-aggressive phenotype by enhancing tumor cell proliferation, invasion, and metastasis." (PMID 37120696, 2023). "The combination of OV-IL15C, an oncolytic HSV-1 that expresses IL15/IL15Rα fusion protein, and off-the-shelf EGFR-CAR-NK showed a synergism in inhibiting tumour growth and improving survival in mice compared to using either as monotherapy." (PMID 37686020, 2023). "Amplification or activating mutations in EGFR can result in hyperactivation of the PI3K signaling pathway, which promotes tumor growth and survival." (PMID 38264122, 2023). "It served as a tumor suppressor to suppress cell proliferation, migration, colony formation, and tube formation, and inhibit tumor growth and angiogenesis by directly targeting EGFR." (PMID 36831545, 2023). "A subsequent in vivo analysis using a nude mouse A375 tumor xenograft model confirmed the ability of EA to inhibit phosphorylation of EGFR and reduce tumor size and weight." (PMID 38002335, 2023). "VEGF, EGFR and other molecular markers in tumor tissue can also be included in scoring systems to provide more accurate estimations of survival time and therapeutic effect." (PMID 37007073, 2023). "In this study, the ALK mutation group had higher edema/tumor ratio (5.66 ± 21.15) than KRAS (5.08 ± 8.70) and EGFR (2.38 ± 6.13) positive mutation groups, implicating worse survival in the ALK mutation group." (PMID 37508989, 2023). "While lowering the affinity of the Nanofitin modules for their respective target, the fusion enables the simultaneous engagement of EGFR and PDL1, which translates into a selective binding to tumor cells co-expressing EGFR and PDL1 only." (PMID 37189383, 2023).
tumor (continued). "EGFR is an important signal involved in tumor growth that can induce tumor metastasis and drug resistance." (PMID 36899380, 2023). "USP9X has been shown to regulate EGFR endocytosis in tumor cell lines by deubiquitinating its endocytic adaptor Eps15 and ubiquitin ligase Itch." (PMID 36653359, 2023). "EGFR facilitates tumor cell survival and metastasis by activating signal transduction cascades, including MAPK, AKT and STAT3." (PMID 37924112, 2023). "Xenograft models showed that the combination of EGFR inhibitor and lorlatinib considerably suppressed tumor regrowth following cessation of these treatments." (PMID 36702855, 2023). "When using an NGS approach to evaluate EGFR status, 37.5% (18/48) of laboratories used a tumour cell threshold of ≥10%, 29.7% (14/48) used ≥5%, and 16.7% (8/48) used a threshold of ≥20%." (PMID 37713929, 2023). "Results also showed a significant inhibitory effect on tumor cells harboring the EGFR WT genotype (p < 0.001), but the effects were slightly weaker than those the ATO treatment group." (PMID 37371816, 2023). "In 62 (16%) of the 393 patients with NSCLC, the tumor had EGFR (46, 12%), ALK (8, 2%) or BRAF V600E (8, 2%) targetable genomic alterations." (PMID 37370865, 2023). "In fact, patients with histologically “low-grade” IDH-wildtype tumours that harbour EGFR amplification, +7/−10, or TERT promoter mutations demonstrate similar patient outcomes to those patients with IDH-wildtype tumours with high-grade histologic features." (PMID 37239289, 2023). "Both estrogen signaling and EGFR signaling can promote proliferation by inducing tumor angiogenesis through vascular endothelial growth factor (VEGF) secretion and other growth factors." (PMID 37700839, 2023). "It has been demonstrated that EGFR plays a role in gliomagenesis but also in tumor cell motility and invasiveness." (PMID 37895074, 2023). "In vivo experiments showed that the circEMB/miR-3184-5p/EGFR axis affected OSA of capable for subcutaneous tumour formation." (PMID 36611218, 2023). "In contrast, transcriptional activation of extracellular organization, the PD-1 signaling pathway, and the PI3K/AKT signaling in cancer pathway positively correlated with increased tumor-stroma interactions and, by extension, EGFR TKI resistance." (PMID 36647832, 2023). "A recent study evaluated 89Zr-anti-EGFR tumor uptake in 10 patients with wildtype K-RAS colorectal cancer and 89Zr-anti-HER3 uptake in 5 HER3-positive solid tumors." (PMID 37174086, 2023). "All these alterations seem converge to the MAPK-ERK intracellular driver, which is over-activated and is responsible of tumor survival even when EGFR inhibitors are used." (PMID 36860319, 2023). "Our findings support the clinical application of DOXA as a safe and accessible treatment option for TNBC, particularly as both c-MET and EGFR are validated targets for neoplasms." (PMID 37924112, 2023). "The regulation of EGFR expression is related not only to the drug resistance of tumor cells but also to the regulation of tumor lymph node metastasis." (PMID 36899380, 2023). "One study reported a significantly higher mean Ktrans value in the EGFR overexpressing tumor group (p < 0.0001), while another study found this to be significantly lower (p = 0.047)." (PMID 37894447, 2023). "Ellagic acid and L-theanine have been shown to reduce EGFR expression and phosphorylation and inhibit tumor growth." (PMID 36978933, 2023). "EGFR expression was higher in TNBC, EGFR overexpression leads to tumor cells receiving stimulus from cytokines, like heparin-binding-EGF, which are formed by the vascular endothelium, and the tumor cells are attached to the tissue with the help of selectins." (PMID 38090376, 2023).
tumor (continued). "Reducing hypersialylation of tumor cells consistently increased the efficacy of HER2 or EGFR antibodies." (PMID 37346044, 2023). "Meanwhile, lower EGFR protein expression was detected in tumor tissues from the mice receiving JAC4 treatment than the vehicle-control mice." (PMID 37240137, 2023). "In particular, 63.3% of (31/49) tumor samples with high NFAT5 expression exhibited a strong p-EGFR staining." (PMID 37429858, 2023). "Of note, also the ADC made of the anti-EGFR cetuximab (Cet) and ZA (Cet-ZA), that we recently described, induced the proliferation of anti-tumor Vδ2 T lymphocytes and their activation against CRC-TAF." (PMID 36765569, 2023). "Animal experiments showed that the combination of FYLM and osimertinib suppressed tumor growth in LLC triple-mutant EGFR xenograft mice." (PMID 36744262, 2023). "We compared RNA-sequencing data from matched primary and recurrent tumour samples (n = 40 patients, 20 with EGFR amplification)." (PMID 36765632, 2023). "HBEGF is expressed in monocytes that can stimulate EGFR on malignant cells to promote tumor progression and metastasis." (PMID 37397378, 2023). "EGFR helps to promote the migratory and aggressive activity of tumor cells, while HER2 plays a key role in promoting internal fluid leakage from tumor cells." (PMID 37688399, 2023). "There were no notable differences in the median percentage of residual viable tumor in resected tumors harboring EGFR/ALK alterations compared with wild type." (PMID 36928818, 2023). "First, it is well known that actionable mutations, such as epidermal growth factor receptor (EGFR) and anaplastic lymphoma kinase (ALK), lead to unregulated proliferation and survival of tumor cells and associated with advanced NSCLC stages." (PMID 36685035, 2023). "Src and phosphoinositide-dependent kinase 1 (PDK1) are involved in EGFR signaling pathways, and their activation is reported to lead to radioresistance of tumor cells." (PMID 37629008, 2023). "Accordingly, EGFR is also one target of anti-angiogenic or tumor vasculature normalization approaches." (PMID 37175811, 2023). "Both external inflammatory stimuli (extrinsic inflammation) and tumor-cell-derived inflammatory mediators (intrinsic inflammation) produced by tumor cells promote EGFR phosphorylation or the activation of EGFR molecular signaling." (PMID 37190301, 2023). "The PKM2-β-catenin interaction was a necessary event for EGFR-driven tumor cell proliferation and brain tumor development." (PMID 37190033, 2023). "The relevance of this regulatory process to cancer becomes significant not only because EGFR activation means the potentiation of tumor growth but also because cancer cells are known to overexpress PGRMC1 and accumulate iron/heme." (PMID 37834119, 2023). "This corroborates the findings that CO is an inhibitor of tumor growth because CO will interfere with the formation of the PGRMC1–heme dimer that is necessary for EGFR activation." (PMID 37834119, 2023). "DNA methylation analysis also showed significant negative correlation between methylation of transcriptional start site and tumor-stroma interaction, whereas the genes within the EGFR pathway have a trend of positive correlation." (PMID 36647832, 2023). "The tumor immunological microenvironment is crucial to immune response and immune escape in EGFR-mutant LUAD patients." (PMID 36756152, 2023). "On the other hand, the presence of EGFR-specific CD8+ T cells was observed in the circulation of HNSCC patients with high EGFR scores, suggesting that EGFR overexpression on tumor cells can elicit specific T cell responses." (PMID 36817764, 2023). "The EGFR inhibitor erlotinib reduced CD4+ effector regulatory T-cell infiltration in the tumor microenvironment and showed better antitumor effects in combination with αPD-1 monoclonal antibody than either treatment alone." (PMID 36892747, 2023).